CFAP53 (cilia and flagella associated protein 53)
Description:
Microtubule inner protein (MIP) part of the dynein-decorated doublet microtubules (DMTs) in cilia axoneme, which is required for motile cilia beating. Regulates motility patterns of both 9+0 and 9+2 motile cilia through differential localization and recruitment of axonemal dynein components (By similarity). Required for centriolar satellite integrity and non-motile cilium assembly. Required for motile cilium formation. Through its role in the beating of primary cilia, involved in the establishment of organ laterality during embryogenesis. Required for sperm flagellum biogenesis and is essential for male fertility (By similarity).
Synonyms: CCDC11; FLJ32743; HTX6
Tractability: Small molecule: a structure with a bound ligand is known. Antibody: its Gene Ontology location is reachable by antibodies, with medium confidence.
Gene: Protein-coding gene on chromosome 18 (50,227,193 to 50,266,504, reverse strand). Ensembl gene ENSG00000172361.
Subcellular location: Cytoplasm, cytoskeleton, cilium axoneme; Cytoplasm, cytoskeleton, flagellum axoneme; Cytoplasm, cytoskeleton, microtubule organizing center, centrosome, centriole; Cytoplasm, cytoskeleton, microtubule organizing center, centrosome, centriolar satellite; Cytoplasm, cytoskeleton, spindle pole; Cytoplasm, cytoskeleton; Cell projection, cilium
Subcellular location (Human Protein Atlas): Basal body; Cytosol; Nuclear membrane; Nucleoplasm
Gene Ontology:
Molecular function: protein binding
Biological process: cilium assembly; determination of left/right symmetry; cilium movement; epithelial cilium movement involved in determination of left/right asymmetry; flagellated sperm motility; manchette assembly; sperm flagellum assembly
Cellular component: axonemal microtubule; axoneme; centriolar satellite; ciliary transition zone; cilium; spindle pole; axonemal A tubule inner sheath; manchette; sperm flagellum; centriole; cytoskeleton; extracellular region; polymeric cytoskeletal fiber
Genetic constraint (gnomAD): Loss-of-function variants: 53 observed, 51.96 expected, observed/expected ratio (o/e) 1.02, 90% interval 0.82 to 1.28. The upper end of that interval is the gene's LOEUF score, 1.28, which puts it in group 5 of 6, group 1 being the genes least tolerant of losing a copy. Missense variants: 593 observed, 589.76 expected, observed/expected ratio (o/e) 1.01, 90% interval 0.94 to 1.08. Synonymous variants: 207 observed, 203.22 expected, observed/expected ratio (o/e) 1.02, 90% interval 0.91 to 1.14.
Homologues: Orthologues: chimpanzee CFAP53 (99% identical), pig CFAP53 (83% identical), dog CFAP53 (81% identical), guinea pig CFAP53 (63% identical).
Diseases named in the same sentence as CFAP53 in open-access papers:
CFAP53 is named in the same sentence as 10 diseases in open-access papers, as found by Europe PMC text mining. Sharing a sentence is not in itself a finding about the gene and the disease. The quoted sentences say what the papers report.
Hydrocephalus (2 papers, 2020 to 2021). Hydrocephalus is an active distension of the ventricular system of the brain resulting from inadequate passage of CSF from its point of production within the cerebral ventricles to its point of absorption into the systemic circulation. "In addition, all of the Cfap53-/- mice examined (14/14) developed hydrocephalus around 3~4 weeks after birth and died by 6 weeks of postnatal life." (PMID 33347437, 2020). "In addition, 32% (8/25) of the Cfap53–/– mice developed hydrocephalus." (PMID 34124066, 2021).
male infertility (2 papers, 2021 to 2024). The inability of the male to effect fertilization of an ovum after a specified period of unprotected intercourse. "To further investigate the cause of male infertility, we first observed the adult Cfap53–/– testis structure at both the gross and histological levels." (PMID 34124066, 2021). "Lately, several genes have been reported to be associated with laterality defects, male infertility, and mild variable respiratory phenotypes such as CCDC11/CFAP53, ENKUR, WDR16/CFAP52, DAW1, and MNS1." (PMID 38920647, 2024). "Thus, the disruption in Cfap53 resulted in male infertility but did not affect the fertility of Cfap53–/– female mice." (PMID 34124066, 2021).
situs inversus (2 papers, 2020 to 2025). A congenital condition in which there is complete right-to-left reversal of the position of the major thoracic and abdominal organs (that is, they are arranged in a mirror image of the normal positioning). "Half of Cfap53-/- mice (7/14) exhibited situs inversus, while 15% (2/14) showed heterotaxy." (PMID 33347437, 2020).
bronchiectasis (1 paper, 2021). Segmental, irreversible dilation of the bronchial tree resulting in the accumulation of secretions which leads to obstruction. "We identified variants in novel PCD candidate genes (CFAP53 and CEP164) in 2 further probands in the non-CF bronchiectasis cohort." (PMID 34556108, 2021).
Neonatal respiratory distress (1 paper, 2022). Respiratory difficulty as newborn. "Conversely, individuals with biallelic MNS1, DNAH9, CFAP53 or RSPH1 mutations have a lower prevalence of neonatal respiratory distress and a later and milder onset of respiratory symptoms." (PMID 36583018, 2022).
Situs inversus totalis (1 paper, 2021). "We analyzed 25 Cfap53–/– mice, and 48% (12/25) of them presented with situs inversus totalis (SIT) and nearly 8% (2/25) had situs inversus abdominalis (SIA)." (PMID 34124066, 2021).
tumor (1 paper, 2024). "Six rare fusion partners were also identified: GOPC, MPRIP, NUP210L, ZCCHC8, CCDC6, and CFAP53, each present in one tumor." (PMID 38835380, 2024).
CFAP53 also shares sentences with these, for which no sentence is quoted: Dextrocardia (1 paper); Infertility (1); primary ciliary dyskinesia (1).